BCL6 (BCL6 transcription repressor)
Diseases named in the same sentence as BCL6 in open-access papers (continued):
Sharing a sentence is not in itself a finding about the gene and the disease.
breast cancer (continued). "A low immunohistochemical expression of Bcl6 has been seen in control breast tissues as well as in G1/G2 breast cancer specimens, while a strong increase of Bcl6 expression in G3 breast cancer specimens was detected." (PMID 29854311, 2018). "For example, BCL6 induced EMT by promoting the ZEB1-mediated transcription repression of E-cadherin in breast cancer cells." (PMID 28583190, 2017). "It has been shown to target BCL6 and is downregulated in breast cancer tissue where overexpression of miR-127-3p or depletion of BCL6 supported its role as a tumor suppressor." (PMID 28621736, 2017). "BCL6 is amplified in ∼50% of breast tumors and is expressed in most breast cancer cell lines, including triple negative breast cancer cell lines." (PMID 26697522, 2015). "In line with previous observation, our data highlight that BCL6 is pivotal in progression of breast cancer cells stimulated by ASCs." (PMID 26439686, 2015). "In the current study, we showed BCL6 as a potential biomarker to predict overall and disease-free survival of breast cancer patients." (PMID 24917186, 2014). "Our current data on manipulating miR-339-5p expression did alter effects of BCL6 on breast cancer cells." (PMID 24917186, 2014). "BCL6 expression was able to induce expression of tumor metastasis-related genes in breast cancer cell lines." (PMID 24917186, 2014). "Expression of BCL6 was restored or knocked down in two breast cancer cell lines (MCF-7 and T47D) using BCL6 cDNA and siRNA, respectively." (PMID 24917186, 2014). "We next determined the potential impact of BCL6 on breast cancer cell migration and invasion capacity." (PMID 24917186, 2014). "After that, we assessed the effects of forced expression or depletion of BCL6 protein on breast cancer cell viability, apoptosis, migration, invasion and gene expression in vitro and in nude mice." (PMID 24917186, 2014). "Expression of BCL6 protein was assessed using in situ hybridization and immunohistochemistry in 127 breast cancer patients and 50 patients with breast benign disease as well as in breast cell lines." (PMID 24917186, 2014). "Expression of BCL6 mRNA and protein was significant higher in breast cancer tissues than in breast benign disease tissues (both P < 0.01)." (PMID 24917186, 2014). "Using gain and loss-of-function approaches, our in vitro data demonstrated that expression of BCL6 did enhance breast cancer cell viability, anchorage-independent growth, migration, and invasion capacity." (PMID 24917186, 2014). "Based on the expression levels of BCL6 in breast cancer cell lines, we therefore selected T47D and MCF-7 cells as model cell lines for the loss-of-function and gain-of-function analyses." (PMID 24917186, 2014). "BCL6 expression has also been observed in skin squamous cell carcinoma, neuroblastoma, melanoma, and breast cancer." (PMID 24917186, 2014). "We assessed the effects of forced expression of BCL6 on breast cancer cell growth, migration, and invasion in vitro." (PMID 24917186, 2014). "Our current data are consistent with these published studies by confirmed the oncogenic effect of BCL6 in breast cancer, similar to those in hematologic malignancies." (PMID 24917186, 2014). "In the current study, we first detected BCL6 expression in breast cancer vs. breast benign disease tissue specimens and found that levels of BCL6 mRNA and protein were significant higher in breast cancer tissues than in breast benign disease tissues." (PMID 24917186, 2014). "Luciferase reporter gene, immunoblot, and qRT-PCR were used to investigate the molecular events after manipulated BCL6 expression in breast cancer cells." (PMID 24917186, 2014).
breast cancer (continued). "We analyzed expression of CXCR4 and cyclinD1 in BCL6 expressed or knocked down breast cancer cell lines and found that expression of these genes was all up-regulated by BCL6 expression." (PMID 24917186, 2014). "After that, we investigated the role of BCL6 expression in regulation of breast cancer cell proliferation, migration, invasion, and survival in vitro and in xenografts models." (PMID 24917186, 2014). "This study investigated the role of BCL6 expression in breast cancer and its clinical significance in breast cancer patients." (PMID 24917186, 2014). "To further determine the effect of BCL6 expression in regulation of breast cancer proliferation and progression in vivo, we injected MCF-7-VEC and MCF-7-BCL6 cells orthotopically into the mammary fat pad of female BALB/c nude mice, respectively." (PMID 24917186, 2014). "It has been reported that BCL-6 is expressed in breast cancer and prevents mammary epithelial differentiation." (PMID 25477702, 2014). "Here, we show that miR-127 induces senescence in human fibroblasts and inhibits the proliferation of breast cancer cells by targeting the oncogene BCL6." (PMID 24282530, 2013). "In contrast, BCL6 expression had a higher expression level in breast cancer cells than normal cells." (PMID 24282530, 2013). "We found that miR-127 was down-regulated in 9 of 10 breast cancer tissues and conversely, that BCL6 expression was up-regulated in breast tumors compared with their corresponding tumor-adjacent tissues." (PMID 24282530, 2013). "In breast cancer tissues, we found that miR-127 was down-regulated, whereas its target,BCL6, was up-regulated." (PMID 24282530, 2013). "Together, these results suggest that miR-127 inhibits cell proliferation by targeting BCL6 in breast cancer cells." (PMID 24282530, 2013). "BCL-6 was found to be overexpressed in breast cancer and in 68% of histological high-grade ductal breast cancers, clinically the most aggressive subgroup of breast cancer." (PMID 20932331, 2010). "However, epigenetic modifications need to be further studied to fully understand their impact on STAT3 and STAT5 transcriptional activity and competition, particularly in the context of competition for BCL6 in breast cancer." (PMID 40507264, 2025). "In addition to hematological tumors, elevated BCL6 protein levels have been observed in various solid tumors such as bladder carcinoma, breast cancer, and ovarian cancer." (PMID 40777995, 2025). "This suggests that STAT5 can inhibit breast cancer progression through modulation of BCL6." (PMID 40507264, 2025). "Furthermore, previous studies have shown that BCL6 is overexpressed in breast cancer and BCL6 expression contributes to breast cancer progression." (PMID 36467500, 2022). "Interestingly, miR-339-5p has been shown to inhibit migration and invasion by targeting BCL6 in breast cancer, ovarian cancer cell lines and in NSCLC." (PMID 34513655, 2021). "Together, these findings are consistent with reduced BCL6 levels enhancing paclitaxel activity in the breast cancer cells by promoting a more sustained G1/S phase cell cycle arrest instead of the more transitory G2/M phase cell cycle arrest observed in the shRNA scramble control cells." (PMID 33932086, 2021). "Similarly, inhibiting BCL6 using a small molecule inhibitor enhanced paclitaxel treatment efficacy both in vitro and in vivo in breast cancer models." (PMID 33932086, 2021). "And BCL6 was found to be expressed in mammary epithelium and also in breast cancer." (PMID 33763120, 2021). "Together, these findings suggest that the benefit of inhibiting BCL6 in combination with paclitaxel in breast cancer could be at least in part explained by the release of CDKN1A suppression." (PMID 33932086, 2021). "Inhibition of BCL6 in breast cancer cells and tumors resulted in increased response to paclitaxel." (PMID 33932086, 2021).
breast cancer (continued). "However, the specific associations among ZBTB16, BCL6, and ZBTB28 and their relevance in breast cancer remain to be established." (PMID 32517789, 2020). "Along with B-cell activation and differentiation, BCL6 plays roles in the DNA damage response, cell cycle regulation, and apoptosis induction of lymphocytes, as well as in the invasion and migration of breast cancer cells." (PMID 33182312, 2020). "Except for malignancy in the lymphoid system, accumulated evidence suggested that overexpression of BCL6 could regulate the progression of various human cancers including gastric cancer, breast cancer, ovarian carcinoma, and GBM." (PMID 30420967, 2018). "Similarly, STAT5A represses BCL6 expression at the transcriptional level in breast cancer cell lines." (PMID 29728695, 2018). "Functionally, besides B-cell activation and differentiation, BCL6 is known to play roles in the DNA damage response, cell cycle regulation and apoptosis induction of lymphocytes, as well as in invasion, migration and proliferation of breast cancer cells." (PMID 29312557, 2017). "However, BCL6 protein was overexpressed in breast cancer tissues, especially in high-grade ductal breast cancer compared to normal mammary gland tissues." (PMID 24917186, 2014). "Future studies will investigate whether target of BCL6 expression could be useful as a novel therapeutic strategy for breast cancer." (PMID 24917186, 2014). "In vitro, the forced expression of BCL6 results in increased proliferation, anchorage-independent growth, migration, invasion and survival of breast cancer cell lines, whereas knockdown of BCL6 expression reduced these oncogenic properties of breast cancer cells." (PMID 24917186, 2014). "The reason for this discrepancy is unknown, but led us to studying the effects of BCL6 on breast cancer cell lines." (PMID 24917186, 2014). "Further studies have revealed that BCL6 is frequently overexpressed in primary breast cancers and breast cancer cell lines, and that BCL6 may play an oncogenic role in breast cancer as well." (PMID 24762632, 2014). "The current study demonstrated the oncogenic property of BCL6 in breast cancer and further study could target BCL6 as a novel potential therapeutic strategy for breast cancer." (PMID 24917186, 2014). "In addition, we found an opposing effect of miR-127 and its target,BCL6, on breast cancer cell proliferation." (PMID 24282530, 2013). "Moreover, we showed that over-expression of miR-127 or depletion of BCL6 expression inhibited breast cancer cell growth." (PMID 24282530, 2013). "Over-expression of miR-127 or depletion of BCL6 inhibits breast cancer cell proliferation." (PMID 24282530, 2013). "Furthermore, metaTF provides a superior characterization of the functional identity of breast cancer epithelial cells, and identifies a novel subset of neural‐regulated T cells within the tumor immune microenvironment, which potentially activates BCL6 in response to neural‐related signals." (PMID 40397381, 2025). "Thus, BCL6 has been associated with resistance to HDAC inhibitors in DLBCL, BCR-ABL1 kinase inhibitors in ALL, cytarabine in AML, paclitaxel in breast cancer, and BET inhibitors in KRAS+ non-small-cell lung cancer." (PMID 39456751, 2024). "During mammary cell growth, prolactin suppresses BCL6 expression through a STAT5A-related mechanism, suggesting that loss of prolactin-STAT5A signaling and concomitant increases of BCL6 may constitute a regulatory switch and facilitate undifferentiated histology and poor prognosis of breast cancer." (PMID 38124049, 2023).
breast cancer (continued). "The authors showed that forced expression of BCL6 results in increased proliferation, anchorage-independent growth, migration, invasion and survival of breast cancer cell lines, whereas knockdown of BCL6 expression reduced these oncogenic properties of breast cancer cells." (PMID 34513655, 2021). "BCL6 exhibits its proinvasive ability in ovarian cancer and breast cancer, and some molecules could perform their anticancer potential by suppressing the expression of BCL6 in ovarian cancer and breast cancer." (PMID 30420967, 2018). "Bcl6 is a transcriptional factor that may play a role in the pathogenesis of breast cancer." (PMID 29854311, 2018). "Thus far, we have demonstrated the effects of BCL6 expression in breast cancer." (PMID 24917186, 2014). "In addition, we will also determine whether BCL6 is a potential biomarker for prediction of breast cancer prognosis or as a therapeutic target for breast cancer patients." (PMID 24917186, 2014). "In primary breast tumors,miR-127 expression is lower, and BCL6 expression is higher than in adjacent normal tissues, suggesting that miR-127 may function as a novel tumor suppressor and that its alteration may contribute to breast cancer development." (PMID 24282530, 2013). "Under normal conditions, ZBTB16 acts as a transcriptional repressor that inhibits breast cancer proliferation and metastasis by upregulating ZBTB28 and antagonizing oncogenic factors such as BCL6/ZBTB27." (PMID 41516402, 2026). "And the correlation between BCL6, NFIB and SMAD3 is only present in CRPC tumor tissues and not in CSPC tumor tissues or other adenocarcinoma tissues (e.g., esophageal cancer and breast cancer)." (PMID 40470696, 2025). "It is reported that Zinc finger and BTB domain containing 16 (ZBTB16) inhibited breast cancer proliferation and metastasis through upregulating ZBTB28 and antagonizing BCL6/ZBTB27." (PMID 38789960, 2024). "Role of BCL6 in other cancer types such as breast cancer were mostly studied in immune deficient mice, however, this mouse model could not well simulate the function of BCL6 in human cancer progression, where immune cells play fundamental role in modulating tumor growth." (PMID 38956432, 2024). "ZBTB16 functions as a tumor suppressor through upregulating ZBTB28 and antagonizing BCL6, leading to inhibition of migration and invasion, reversal of EMT, and suppression of cell proliferation in breast cancer." (PMID 38789960, 2024). "BCL6 has been characterized as an oncogene and ZBTB28 acts as a tumor suppressor gene (TSG) in breast cancer." (PMID 32517789, 2020). "Further, BCL6 was suggested as a drug target in combination with STAT3 in NSCLC cells, as well as in breast cancer cells." (PMID 32234966, 2020). "For example, in T-47D and SK-BR-3 breast cancer cell lines, STAT5a and STAT3 differentially regulated BCL-6 expression, a protein involved in apoptosis." (PMID 32633727, 2020). "STAT3 was found to increase the expression of BCL6 in breast cancer cells; however, the STAT5-mediated repression of BCL6 in these cells was dominant, because STAT5 displaced STAT3 from the shared DNA-binding site." (PMID 29728695, 2018). "In breast cancer cells, STAT3 leads to increased expression of BCL6 and STAT5 mediates repression of this gene." (PMID 24762632, 2014).
breast cancer (continued). "In conclusion, our current study demonstrated that the reduced miR-339-5p expression [our previous data] promoted BCL6 expression, which in turn induces cyclinD1 and CXCR4 expression for induction of breast cancer cell proliferation and invasion." (PMID 24917186, 2014). "However, it remains unknown how BCL6 contribute to breast cancer development or progression." (PMID 24917186, 2014). "Data from the luciferase assay showed that ZBTB16 suppressed the promoter activity of BCL6 and enhanced that of ZBTB28, indicating that ZBTB16 might play an anti-tumor role in breast cancer through regulating ZBTB28 and BCL6." (PMID 32517789, 2020). "In breast cancer, Bcl6 prevents mammary epithelial cell differentiation, induces epithelial mesenchymal transition (EMT), and it has been proposed as a molecular target for breast cancer therapy." (PMID 29854311, 2018). "Alternatively, BCL6 could regulate multiple other molecules like KLF6, a direct target of BCL6 in breast cancer cells." (PMID 29312557, 2017). "Expression of BCL6 mRNA in breast cancer and non-tumorigenic cell lines was analyzed by qRT-PCR and the data showed levels of BCL6 mRNA were significantly higher in breast cancer cell lines than in non-tumorigenic mammary epidermal cells (P < 0.05)." (PMID 24917186, 2014). "We identified PRL-suppression of BCL6 transcript and protein based on this global transcript analysis of T47D xenotransplants tumors, and we reported a negative correlation between levels of BCL6 protein and Nuc-pYStat5 in clinical breast cancer specimens." (PMID 23758962, 2013). "Indeed, BCL6 has been involved in the pathogenesis of B-acute lymphoblastic leukemia (B-ALL), chronic myeloid leukemia (CML), breast cancer, and non-small cell lung cancer (NSCLC), and thus its dysregulated gene expression is an attractive target for therapeutic interventions." (PMID 37835497, 2023). "The effect of BCL6 inhibition on cell viability was observed in both TNBC and ER+ paclitaxel‐treated cells, suggesting that inhibition of BCL6 could be incorporated as a potential strategy across breast cancer subtypes and not just in a subset of patients." (PMID 33932086, 2021). "Additionally, the availability of a small molecule inhibitor that targets resistance screen hit BCL6 (BCL6i, 79‐6), and the lack of prior studies assessing the effect of BCL6 on drug response, prompted us to investigate the role of BCL6 in paclitaxel response in breast cancer." (PMID 33932086, 2021).